DIAPH3 (diaphanous related formin 3)
Diseases named in the same sentence as DIAPH3 in open-access papers (continued):
Sharing a sentence is not in itself a finding about the gene and the disease.
pancreatic cancer (continued). "In order to further verify the functions of DIAPH3 in promoting the proliferation of pancreatic cancer, we designed an shRNA targeted to human DIAPH3, constructed DIAPH3 stable knock down cell line in Mia Paca‐2 and CFPAC‐1 cells and tested its knock down efficiency using Western Blot." (PMID 33345387, 2021). "In summary, DIAPH3 can promote the invasive capacity of pancreatic cancer cells." (PMID 33345387, 2021). "Through GO analysis on the Metascape website, we found that the interacting proteins of DIAPH3 were mainly selenoamino acid metabolic enzymes, indicating that DIAPH3 may affect the metabolism of selenoamino acids in pancreatic cancer." (PMID 33345387, 2021). "In this study, we investigated the expression pattern, function and molecular mechanism of DIAPH3 in pancreatic cancer, and our observations indicate DIAPH3 could promote pancreatic cancer progression by activating selenoprotein TrxR1‐mediated antioxidant effects." (PMID 33345387, 2021). "However, the specific mechanism of DIAPH3 in the occurrence and development of pancreatic cancer is still unknown." (PMID 33345387, 2021). "In addition, diaphanous-related formin-3 (DIAPH3) also upregulated cellular Se level and selenoprotein, TXNRD1, in pancreatic cancer cells." (PMID 36211509, 2022). "Similarly, when we knocked down DIAPH3 in pancreatic cancer cells Mia Paca‐2 and CFPAC‐1, the non‐anchored growing ability of pancreatic cancer cells was significantly blocked." (PMID 33345387, 2021).
autism (6 papers, 2013 to 2024). Persistent deficits in social interaction and communication and interaction as well as a markedly restricted repertoire of activity and interest as well as repetitive patterns of behavior. "In chromosome 13, rs17057528 (P = 8.82 × 10−09) is in DIAPH3, identified as an autism risk gene, and is also implicated in hearing loss and impairment of speech perception." (PMID 38811692, 2024). "This seems in line with clinical findings in humans, where DIAPH3 was linked to autism in two independent studies." (PMID 35681420, 2022). "The second case reported a de novo missense mutation within the DIAPH3 FH2 domain together with another de novo mutation in a known autism-associated gene, SET2." (PMID 35681420, 2022). "The first case to relate DIAPH3 with autism was that of a boy who inherited a variant (p.Pro614Thr) in the FH1 domain of one of the alleles and a large genomic deletion in the other, DIAPH3 being one of the genes considered in the study." (PMID 34685534, 2021). "DIAPH3 seems to be the formin gene most strongly linked to autism, as suggested by the identification of variants in autistic individuals." (PMID 34685534, 2021). "In humans, two clinical studies point to DIAPH3 as an autism susceptibility gene." (PMID 33899739, 2021). "This was found in a second case that presented a missense replacement in the region of DIAPH3 encoding the FH2 domain and a second mutation in SET2, a gene associated with autism and other neurodevelopmental disorders." (PMID 34685534, 2021). "The responsible gene(s) for the combined phenotypes has not been yet identified but this region harbors potential candidate genes such as DIAPH3 with suggested connections to both autism and language impairment." (PMID 23840741, 2013). "It has been suggested that DIAPH3 might be involved in synaptic activity and function downstream of SHANK3 (chromosome 22q13), a well-documented autism susceptibility gene." (PMID 23840741, 2013). "This double-hit case is very rare and indicates that, in the absence of a double mutation in DIAPH3, at least one extra mutation may be needed in one or more autism-related genes to produce the phenotype." (PMID 34685534, 2021).
glioblastoma (5 papers, 2018 to 2024). The most malignant astrocytic tumor (WHO grade IV). "We found that 36% and 1% of the TCGA glioblastoma samples exhibit copy number alterations and mutations in DIAPH3, respectively." (PMID 38454929, 2024). "In this work, we explored the relationship between DIAPH3 levels and survival of glioblastoma patients." (PMID 38454929, 2024). "We show that DIAPH3 is mostly expressed in proliferating malignant cells in glioblastoma and that the methylation of three CpG sites in the DIAPH3 promoter contributes to its downregulation." (PMID 38454929, 2024). "In this study, we report that DIAPH3 expression is positively correlated with overall survival of patients with MGMT-methylated glioblastoma." (PMID 38454929, 2024). "In this study, we investigated the expression of DIAPH3 in glioblastoma and uncovered a positive correlation between DIAPH3 expression level and patients’ survival." (PMID 38454929, 2024). "In patient-derived glioblastoma stem-like cells, indirect evidence from diaphanous formin modulator studies suggests that DIAPH3 contributes to invasion mechanisms." (PMID 38454929, 2024). "According to TCGA, 36% of glioblastoma patients harbor copy number alterations of DIAPH3, most of which (35%) are copy losses, whereas only 1% of these patients have a mutation in DIAPH3." (PMID 38454929, 2024). "We analyzed DIAPH3 expression in glioblastoma samples from the cancer genome atlas (TCGA)." (PMID 38454929, 2024). "Given the association of DIAPH3 loss with aneuploidy in murine embryonic neural stem cells, and the negative impact of aneuploidy on cancer prognosis, we investigated whether DIAPH3 levels could affect the prognosis of human glioblastoma." (PMID 38454929, 2024). "We evaluated DIAPH3 relative expression by quantitative reverse transcription PCR in 73 IDH-wild-type glioblastomas from patients operated on between May 2013 and August 2019." (PMID 38454929, 2024). "We scrutinized the expression of DIAPH3 at single cell level and detected an overlap with MKI67 expression in glioblastoma proliferating cells, including neural progenitor-like, oligodendrocyte progenitor-like and astrocyte-like states." (PMID 38454929, 2024). "Importantly, the methylation levels at these three CpG sites were negatively correlated with DIAPH3 expression (Padj=0.008, 0.002, and 0.003 for CpG 6, CpG 28 and CpG 29, respectively), suggesting that the methylation of these sites contributes to DIAPH3 downregulation in glioblastoma samples." (PMID 38454929, 2024). "To corroborate this finding, we analyzed the relationship between DIAPH3 expression and OS in the TCGA IDH-wild-type glioblastoma cohort (n=109)." (PMID 38454929, 2024).
lung adenocarcinoma (5 papers, 2021 to 2023). A carcinoma that arises from the lung and is characterized by the presence of malignant glandular epithelial cells. "In lung adenocarcinoma, DIAPH3 binds to STK38 protein and activates extracellular signal-regulated kinase signal transduction, promoting the growth of lung cancer cells." (PMID 36750200, 2023). "In lung adenocarcinomas, the knockdown of DIAPH3 inhibited tumorigenesis in both nude mice and in de novo mouse models via impaired ERK signaling." (PMID 34771513, 2021).
microcephaly (5 papers, 2016 to 2021). A congenital or acquired developmental disorder in which the circumference of the head is smaller than normal for the person's age and sex. "We also used a conditional approach to delete Diaph3 specifically in the cerebral cortex and report that this causes a marked depletion of cortical neurons, microcephaly, locomotor impairment, and social interaction defects." (PMID 33899739, 2021). "Inactivation of the Diaph3 gene causes a massive loss of cortical progenitor cells, with subsequent depletion of intermediate progenitors and neurons, and results in microcephaly." (PMID 27848932, 2016). "Here the authors show that Diaph3 is critical for spindle checkpoint activity in cortical progenitor cells as the loss of Diaph3 leads to apoptosis of progenitor cells and eventually results in microcephaly in mice." (PMID 27848932, 2016). "The severity of the Diaph3 phenotype (that is, embryonic lethality) might have precluded the establishment of a causal link between microcephaly and DIAPH3 loss-of-function mutations." (PMID 27848932, 2016). "Therefore, the role of DIAPH3 in fidelity of nuclear division and the cell loss observed in Diaph3 cKO mice may be more instrumental to the emergence of microcephaly in Diaph3 cKO mice than its role in oriented cell division." (PMID 33899739, 2021). "In this work, we report that the conditional deletion of Diaph3 in the mouse cerebral cortex dramatically affects neurogenesis and leads to microcephaly and autistic-like behavior, with typical altered motor activity and social interactions." (PMID 33899739, 2021). "The involvement of Diaph3 in microcephaly suggests a functional redundancy and/or divergent roles of Diaphanous genes in humans and mice." (PMID 27848932, 2016). "Our data identify Diaph3 as a major guard of cortical progenitors, unravel novel functions of Diaphanous formins and add insights into the pathobiology of microcephaly." (PMID 27848932, 2016). "The specific KO of Diaph3 in the brain cortex of mice alters the spindle components, leading to fewer proliferative divisions and more neurogenic divisions in apical neural progenitor cells, and thereby to a thinner cortex (microcephaly)." (PMID 34685534, 2021). "DIAPH3 (diaphanous related formin 3) is a gene involved in cell movement and adhesion, and may be involved in autism spectrum disorders, as well to microcephaly." (PMID 30645614, 2019).
epithelial ovarian cancer (4 papers, 2014 to 2022). "mDia2, which is encoded by DIAPH3, increased invasive cell egress from epithelial ovarian cancer spheroids." (PMID 29596520, 2018). "In prostate and ovarian cancer studies, DIAPH3 was lost steadily from early through late stage disease models, and was accompanied by a disorganized cytoskeleton depleted of F-actin and a more aggressive phenotype." (PMID 24587343, 2014).
lung carcinoma (4 papers, 2016 to 2023). "DIAPH3 has been identified as the binding protein of STK38 that impairs the interaction between STK38 and MEKK and activates ERK signaling to trigger off tumorigenesis of lung cancer." (PMID 34405015, 2021).
auditory neuropathy autosomal dominant 1 (3 papers, 2022 to 2024). "For instance, a point mutation in the 5’ untranslated region of DIAPH3 increases DIAPH3 expression, leading to auditory neuropathy autosomal dominant 1 (AUNA1), suggesting that this mutation may impede the binding of a transcriptional repressor." (PMID 38454929, 2024). "Interestingly, the overexpression of one of the altered genes, Diaph3, is responsible for autosomal dominant auditory neuropathy-1 (AUNA1) in humans and mice, and is associated with defects in the inner hair cell stereocilia." (PMID 36400760, 2022). "Mutations in the human DIAPH3 gene, which is located on chromosome 13, have been involved in nonsyndromic, autosomal dominant auditory neuropathy 1 (AUNA1, MIM #609129)." (PMID 35681420, 2022). "In particular, heterozygous mutations in DIAPH1 are responsible for autosomal dominant deafness with or without thrombocytopenia (DFNA1, MIM #124900), whereas regulatory mutations inducing the overexpression of DIAPH3 cause autosomal dominant auditory neuropathy 1 (AUNA1, MIM #609129)." (PMID 35681420, 2022).
cervical cancer (3 papers, 2021 to 2023). A primary or metastatic malignant neoplasm involving the cervix. "Combined with the univariate cox and multivariate cox analysis, it indicated that the expression of DIAPH3 was an independent prognostic risk index of cervical cancer." (PMID 34659408, 2021). "Using online analysis tools, the relationship between the expression of DIAPH3 in cervical cancer and the infiltration of common immune cells was determined." (PMID 36750200, 2023). "The expression of DIAPH3 in cervical cancer was observed to be negatively correlated with B cell and macrophage infiltration by TIMER analysis." (PMID 36750200, 2023). "KM survival analysis revealed that the abnormal increase of DIAPH3 in cervical cancer was an unfavorable factor for the prognosis of patients." (PMID 36750200, 2023). "The expression of DIAPH3 in cervical cancer was significantly different from that in normal cervical tissues." (PMID 36750200, 2023). "In cervical cancer, the expression of DIAPH3 was negatively correlated with the B cell group, macrophage group, dendritic cell group, and effector T cell group and positively correlated with lymphoid progenitor cells and Th2 CD4+ T cells." (PMID 36750200, 2023). "We used the western blot to verify the expression of DIAPH3 in three pairs of cervical cancer and adjacent normal tissues." (PMID 36750200, 2023). "Using the pan-cancer analysis in the Tumor Immune Estimation Resource (TIMER) database and TCGA database, we observed that DIAPH3 was highly expressed in cervical cancer and multiple tumors." (PMID 36750200, 2023). "In this study, we detected the clinical samples of cervical cancer and explored the expression of DIAPH3 using western blot and qRT-PCR." (PMID 36750200, 2023). "There have been few studies on cervical cancer; however, one study has reported that knocking down DIAPH3 in cervical cancer cell lines can inhibit cell proliferation." (PMID 36750200, 2023). "Accordingly, these data indicated that knockdown of DIAPH3 inhibited the proliferation of cervical cancer cells through inactivating the mTOR signaling pathway." (PMID 34659408, 2021). "In our study, we firstly explored the notion that knockdown of DIAPH3 inhibits the proliferation of cervical cancer cells through inactivating the mTOR signaling pathway." (PMID 34659408, 2021). "We firstly reported that DIAPH3 was overexpressed in cervical cancer and enhanced the ability of CC cell proliferation." (PMID 34659408, 2021). "Similarly, the quantitative reverse-transcription-polymerase chain reaction (RT qPCR) assay detected the expression of DIAPH3 in four pairs of cervical cancer and adjacent normal tissues." (PMID 36750200, 2023). "DIAPH3 knockdown inhibits the proliferation of cervical cancer cells." (PMID 36589226, 2022). "We revealed that DIAPH3 promoted proliferation through mTOR signaling pathway in cervical cancer." (PMID 34659408, 2021). "In this study, the DIAPH3 gene was screened using bioinformatic tools and observed to be highly expressed in various cancers, including cervical cancer, which may be involved in several processes of tumor development and is related to the changes in the tumor immune microenvironment." (PMID 36750200, 2023). "We hope that DIAPH3 may become a novel therapy target in cervical cancer." (PMID 34659408, 2021). "Conclusively, the expression of DIAPH3 in cervical cancer is significantly higher than that in normal cervical tissue." (PMID 36750200, 2023).
metastatic tumor (3 papers, 2012 to 2022). "Further, DIAPH3 was reported to be down-regulated in cancer cells and its down-regulation was associated with aggressive or metastatic disease state in various malignancies." (PMID 33297976, 2020). "Impairment of DIAPH3 function may lead in wound healing process, which is linked to major signaling pathways involved in metastatic tumor growth, including EGFR, TGF‐beta, and FGFR, of which EGFR is a critical component." (PMID 35538918, 2022).
triple-negative breast carcinoma (3 papers, 2021 to 2023). An invasive breast carcinoma which is negative for expression of estrogen receptor (ER), progesterone receptor (PR), and human epidermal growth factor receptor 2 (HER2). "Nevertheless, one study investigating triple-negative breast cancer showed that DIAPH3 expression was significantly decreased in cancer tissues." (PMID 35201449, 2021).
glioma (2 papers, 2019 to 2026). A benign or malignant brain and spinal cord tumor that arises from glial cells (astrocytes, oligodendrocytes, ependymal cells). "We isolated cancer stem-like cells and assessed their sensitivity to ionizing radiation and found that DIAPH3 regulates the resistance of glioma stem-like cells to irradiation." (PMID 41872154, 2026). "DIAPH3 was modestly, yet significantly, upregulated in grades II-IV gliomas, relative to the normal brain and was expressed in U87 and U251 glioma cells." (PMID 30897774, 2019). "Here, we investigated the role of DIAPH3 in glioma genesis in mouse models." (PMID 41872154, 2026).
neuropathy (2 papers, 2011 to 2020). A disorder affecting the nervous system that manifests with pain, tingling, numbness, and/or muscle weakness. "Clinical and electrophysiological findings along with the good results obtained after cochlear implantation suggest a nonsyndromic autosomal dominant auditory neuropathy 1 (AUNA1) via a synaptic lesion, listing DIAPH3 mutations as a postsynaptic neuropathy." (PMID 32290039, 2020).
bladder cancer (1 paper, 2018). "We further evaluated the expression of DIAPH3, LMAN1, PPP2R5E, and UHMK1 in bladder cancer cell lines upon LINC00857 knockdown." (PMID 29856124, 2018).
ciliopathies (1 paper, 2021). "Given the similarity between DIAPHs 1, 2, and 3, and since mutations of DIAPH2 and DIAPH3 in humans give phenotypes commonly seen in ciliopathies, we reasoned that DIAPH2 and DIAPH3 proteins may also play roles in ciliogenesis and cilia maintenance." (PMID 33872598, 2021).
hearing (1 paper, 2022). "Such defects are seen, among others in mutants overexpressing DIAPH3, suggesting a possible link between the microtubule-modulating activity of the DIAPH3 protein, the (kino)cilia function, and hearing loss." (PMID 35681420, 2022).
invasive breast carcinoma (1 paper, 2018). A carcinoma that infiltrates the breast parenchyma. "Interestingly, DIAPH3 expression was decreased in micro-dissected tumor adjacent stroma derived from invasive breast carcinoma." (PMID 29596520, 2018).
liver cancer (1 paper, 2021). An epithelial or non-epithelial malignant neoplasm that arises from the liver. "Consistently, DIAPH3 promotes the growth, migration and metastasis of liver cancer cells by activating the β‐catenin/TCF signalling pathway." (PMID 33345387, 2021). "Previous studies reported that DIAPH3 promoted the growth, invasion and metastasis of liver cancer by activating β‐catenin/TCF signalling pathway." (PMID 33345387, 2021).
lymph node metastasis (1 paper, 2021). "In TNBC, DIAPH3 expression was associated with TNM stage and lymph node metastasis, but not with tumor size in patients." (PMID 34771513, 2021).
metastatic prostate carcinoma (1 paper, 2022). A carcinoma that arises from the prostate gland and has spread to other anatomic sites. "The gene encoding the cytoskeleton modulator DIAPH3 is lost frequently in metastatic prostate cancer, and DIAPH3 silencing induces a shift to an amoeba-like tumor phenotype in a variety of cellular settings." (PMID 36434693, 2022).
microcephalic osteodysplastic primordial dwarfism type I (1 paper, 2021). A microcephalic osteodysplastic primordial dwarfism that has material basis in homozygous or compound heterozygous mutation in the RNU4ATAC gene, encoding a small nuclear RNA (snRNA) component of the U12-dependent (minor) spliceosome, on chromosome 2q14.2. "In support of this, patients with microcephalic osteodysplastic primordial dwarfism type 1 (MOPD 1) syndrome display a 50% reduction in DIAPH3 expression." (PMID 33899739, 2021).